CDK4 (cyclin dependent kinase 4)
Diseases named in the same sentence as CDK4 in open-access papers (continued):
Sharing a sentence is not in itself a finding about the gene and the disease.
infection (33 papers, 2009 to 2025). The state of being infected such as from the introduction of a foreign agent such as serum, vaccine, antigenic substance or organism. "This study aimed to provide a comprehensive understanding of the occurrence of CDK4/6 inhibitor-associated infections." (PMID 39011505, 2024). "This study aimed to analyze the occurrence of infections associated with the CDK4/6 inhibitors (palbociclib, ribociclib and abemaciclib) based on the real-world data from the US Food and Drug Administration Adverse Event Reporting System (FAERS) database." (PMID 39011505, 2024). "Infection-related AEs were highly associated with three CDK4/6 inhibitors, especially palbociclib and ribociclib, based on the real-world data from the FAERS database." (PMID 39011505, 2024). "A disproportionality analysis was conducted to assess the potential association between infection-related AEs and CDK4/6 inhibitors." (PMID 39011505, 2024). "According to the manufacturer’s instructions, infection is a common adverse reaction associated with CDK4/6 inhibitors." (PMID 39011505, 2024). "In this study, infection-related AEs for abemaciclib accounted for 1.24% of all AEs associated with abemaciclib, and it presented the lowest number of infection-related AEs among the three CDK4/6 inhibitors." (PMID 39011505, 2024). "Our study showed that infection-related AEs for ribociclib accounted for 8.58% in all AEs associated with ribociclib, which was the highest proportion of infection-related AEs among the three CDK4/6 inhibitors." (PMID 39011505, 2024). "In our cohort, 4 patients discontinued the CDK4/6i for reasons other than disease progression and remained on ET alone (2 due to patient preference during the COVID pandemic; 1 due to recurrent infection; 1 due to liver toxicity)." (PMID 40683861, 2025). "In the current investigation, it was observed that the expression of CDK4 was reduced while CDK6 expression was increased following LPS infection." (PMID 40136393, 2025). "Given the potential clinical benefits, a comprehensive study of infection-related adverse events (AEs) of these three CDK4/6 inhibitors in post-marketing setting is needed to better evaluate the occurrence of infection." (PMID 39011505, 2024). "Based on the PTs enrolled for each CDK4/6 inhibitor, we extracted infection-related AEs from 2015Q1 to 2022Q3 from the FAERS." (PMID 39011505, 2024). "We further analyzed the occurrence of infection-related AEs in patients treated with the three CDK4/6 inhibitors." (PMID 39011505, 2024). "Since efficient cell growth requires double infection with mutant CDK4 and Cyclin D1-expressing lentiviruses, an estimated 64% of cells would be doubly-infected, while the rest (∼36%) would have a single transgene, mutant CDK4 or Cyclin D1." (PMID 32269992, 2020). "The results showed that HP-CagA+ infection increased the distribution of CDK4 and CyclinD1 in the nucleus, and co-localization was observed." (PMID 31905669, 2019). "To exclude this possibility, we reactivated both myotubes and quiescent fibroblasts by infection with the mutant adenovirus, dl520, or expression of cyclin D1 and cdk4." (PMID 20644635, 2010). "Both studies also consistently showed a regulation of Cdk2 and Cdk4/6 upon infection of epithelial cells with P. gingivalis." (PMID 19689803, 2009). "Therefore, this study is of great significance for evaluating the occurrence of infection-related AEs for CDK4/6 inhibitors based on real-world data from the FAERS database from 2015Q1 to 2022Q3." (PMID 39011505, 2024). "Although AEs associated with CDK4/6 inhibitors have been widely reported, comprehensive studies on infection-related AEs associated with CDK4/6 inhibitors are lacking." (PMID 39011505, 2024). "We then addressed the question of whether the time point of pretreatment with CDK4/6i had an impact on the enhanced oncolytic activity and did not observe any obvious differences between 24 h pretreatment with CDK4/6i before infection or parallel treatment." (PMID 35948546, 2022).
infection (continued). "We found that human bronchial epithelial cells immortalized with hTERT and CDK4 (HBE3-KT) were refractory to infection and expressed undetectable levels of hACE2, but they did express the TMPRSS2 cell surface protease that activates the SARS-CoV-2 spike glycoprotein." (PMID 34724828, 2021). "This hypothesis was confirmed by infection of CD56 sorted 01Abic cells with CDK4." (PMID 21798090, 2011). "In conclusion, our study demonstrated that infection of gastric epithelial cells by H. pylori led to increased PGRN expression, which regulated the expression of CDK4 by activating the PI3K/Akt signal pathway." (PMID 35880418, 2022). "The infection of NS1-BP-overexpressing ESCC cells with c-Myc lentivirus to achieve ectopic overexpression of c-Myc restored the levels of survivin, CDK4, and p27." (PMID 29871674, 2018). "Ninety-six hours after infection, total RNA was extracted and the transcript levels for LAST, CCND1, CCNE1, CDK2, CDK4 and c-Myc were analyzed by real-time RT-PCR." (PMID 29199958, 2017). "Genes involved in cell cycle CDK4, CDK5, Cyclin E1, CKN2B, CDKN2D were down-regulated at all time-points post infection." (PMID 20828378, 2010). "For example, CycD, CDK4 and CDK6, were upregulated in HIGK infected with the mixed microflora compared to HIGK transcript levels in response to mono-infection with P. gingivalis." (PMID 19689803, 2009). "Interestingly, at very early stages of the infection, harmaline interferes with the binding of the IE complex to the ICP0 promoter, and several βCs can inhibit cdk4 and HDACs." (PMID 38732185, 2024). "Transcripts for c-Myc, Myb, CDK4, TNFα, IFNα, and IFNγ were upregulated during early infection with the virus (3d post-infection) alone but not at 7 days post-infection." (PMID 38279262, 2024). "Of the tissues evaluated in the present study, gene expression in the HRT was the most severely impacted by infection, with significant decreases in all three cell cycle promoters (CDK1, CDK2 and CDK4) and the largest increase in expression of their inhibitor CDKN1A." (PMID 35189966, 2022). "One important finding of the described combination therapy with CDK4/6i and XVir-N-31 is the observation that RB expression remains downregulated throughout viral life cycle in the combination therapy whereas E2F1 level recover already 12 h past infection." (PMID 35948546, 2022). "In addition to CDK4 and IFITM proteins, targeting of SLC35B2 in both SARS-CoV-2 and OC43 Vero E6 screens increased resistance to infection, suggesting that it is a pan-HCoV host factor in this cell line." (PMID 35086559, 2022). "Relative cell growth and RT-qPCRs show that CDK4 overexpression does not affect proliferation arrest markers at day 12 post infection in senescent IMR-90 cells." (PMID 34676390, 2021). "Following 24 h of MDRV infection, protein expression levels of p10.8, BiP, p-PERK, p-eIF2α, CHOP, cleaved-Caspase12, cleaved-Caspase3 all increased, while expression levels of Cyclin E, CDK2, CDK4 decreased." (PMID 29977231, 2018). "We demonstrated that cyclinD, CDK4, CDK6, cyclinE1 and CDK2 are down-regulated after EV-D68 infection, which could explain the ability of EV-D68 to inhibit the transition from G0/G1 to S phase." (PMID 28229049, 2017). "Nonetheless, since the effect of this combination therapy is also visible in cells that are not primed with CDK4/6i before infection, we can exclude that cell cycle synchronization in G1/G0 is the major underlying molecular mechanism of this combination therapy." (PMID 35948546, 2022).
infection (continued). "As for viral replication, we could not observe a difference of infection after treatment with CDK4/6i 4 h post-infection, indicating that infectivity is not the critical factor for increased potency of Ad vectors after CDK4/6i treatment." (PMID 35948546, 2022). "In addition, one of the genes, cdk4/6, necessary for cells to enter the G1 phase from the G0 phase, was significantly up-regulated in the CSBV Bces-Po19 S group, indicating that CSBV Bces-Po19 infection might induce G0/G1 phase arrest in the host cells." (PMID 35746687, 2022). "We investigated the impact of the MAPK family inhibitors Selumetinib (MEK1 and MEK2) and JNK-IN-8 (JNK family), and the impact of CDK family kinase inhibitors Roscovitine (CDK2, CDK5), Dinaciclib (CDK4, CDK6), and the non-specific CDK/Crk during infection (Fig. EV2A,B)." (PMID 38177504, 2024).
hematological malignancies (15 papers, 2018 to 2025). "We reviewed the existing literature to identify those specific miRNAs that have been linked to response to CDK4/6 inhibitors in solid tumors and hematological malignancies." (PMID 34439268, 2021). "Herein, we systematically review all microRNAs associated with response to CDK4/6 inhibitors in solid tumors and hematological malignancies." (PMID 34439268, 2021). "Accordingly, several studies have demonstrated the role of CDK4/6 in solid tumors and hematologic malignancies, as well as the robust antitumor activity associated with CDK4/6 inhibition." (PMID 30443290, 2018). "Notably, amplification or rearrangements of the CDK4-encoding gene have been shown to cause overexpression of CDK4 protein that has almost universally been associated with many types of solid tumours and hematologic malignancies." (PMID 34930213, 2021). "This case report describes a patient with solid tumors and hematological malignancies who developed PML while receiving a CDK4/6 inhibitor." (PMID 40259166, 2025). "CDK4/6 specific inhibitors represent a promising valuable choice for the treatment of hematological malignancies." (PMID 36033505, 2022). "More recent pre-clinical studies have shown promising effects of CDK4/CDK6 inhibitors in certain hematologic malignancies." (PMID 35804842, 2022). "present in their recent work an extensive and detailed collection of preclinical and clinical studies conducted with several CDK4/6 inhibitors in hematological diseases." (PMID 36033505, 2022). "Ribociclib (LEE011) was tested in phase II trials in patients with solid tumors and/or hematologic malignances with CDK4/6 pathway‐activated tumors (NCT02187783), but most patients succumbed to progressive disease." (PMID 35229492, 2022). "The effect of CDK4/6 inhibitors is cytostatic in cell culture and animal models of solid tumors; in contrast, the effect of CDK4/6 inhibitors is cytotoxic in selected hematological diseases." (PMID 34440587, 2021). "Dual CDK4/6 inhibitors have achieved great success in the treatment of hormone-receptor-positive breast cancer and have shown promising results in several solid tumors and hematological malignancies." (PMID 36046234, 2022). "CDK4/CDK6 is a well-established target in applied oncology and has also been discussed in the context of hematologic malignancies." (PMID 35804842, 2022). "CDK4/6Is palbociclib, abemaciclib, and ribociclib are already FDA-approved for solid neoplasms, raising hopes for a subsequent clinical implementation in hematological malignancies in the near future." (PMID 34065376, 2021). "Because both proteins play key roles in these and other hematological malignancies, we have analyzed the therapeutic potential of ON108110, a novel dual specificity ATP-competitive inhibitor of protein kinase CK2 as well as CDK4/6 in MCL and T-ALL." (PMID 30701029, 2018). "In addition, a more specific CDK4 inhibitor (i.e., PF-07220060) and two more broad CDK4/6 inhibitors (i.e., FLX925 and ETH-155008) are under examination in the context of certain advanced solid tumors and hematologic malignancies." (PMID 37626854, 2023).
adenocarcinoma (11 papers, 2011 to 2025). A common cancer characterized by the presence of malignant glandular cells. "Emerging data support the use of immune checkpoint inhibitors in squamous BGC and targeted agents (e.g., mTOR/CDK4/6 inhibitors) in adenocarcinoma." (PMID 41375020, 2025). "We utilized MMTV-rtTA/tetO-HER2 transgenic mice, which develop spontaneously arising, cyclin D1 and Rb-expressing, CDK4/6i–sensitive adenocarcinomas within developmentally normal, mature mammary glands." (PMID 38047585, 2024). "CDK4 appears to be more highly expressed in adenocarcinomas compared to the other two histologic subtypes." (PMID 21477379, 2011). "In recent years, CDK4/6 inhibitors have been used in the treatment of adenocarcinoma." (PMID 36457244, 2023). "The previous study has shown that adenocarcinoma cell lines are more sensitive to CDK4 than squamous cancer cell lines.Unfortunately, recent clinical trials of CDK4/6i as single agents in non-small cell lung cancer (NSCLC) have not achieved satisfactory results." (PMID 35686110, 2022). "On the contrary, CDK4 amplification is only found in 5.3% of adenocarcinoma." (PMID 35585228, 2022). "Several of the identified mGISTIC regions harbored known or putative adenocarcinoma driver candidates, such as EGFR, MDM2, KRAS, MYC, TERT, MET, CCND1, NKX2-1/TITF1, CDK4, ERBB2, ID1, RB1, CDKN2A and PTEN." (PMID 24205279, 2013). "For non-intestinal BG adenocarcinoma, a whole-genome case revealed somatic PTEN loss (exons 2–5) together with CCND1 amplification; these findings supported everolimus (mTOR inhibitor) followed by palbociclib (CDK4/6 inhibitor) with radiologic responses under compassionate use." (PMID 41375020, 2025).
benign tumors (5 papers, 2012 to 2023). "For adipocytic tumors, the majority of the benign tumors had a negative expression of p16 (6/8; 75%) and CDK4 (8/8; 100%) while the majority of malignant and intermediate tumors had positive p16 (7/7; 100%) and CDK4 (6/7; 85.7%) expression." (PMID 37016649, 2023).
CNS tumors (5 papers, 2020 to 2024). "However, the utility of CDK4/6 for treatment of CNS tumors is limited due to poor penetration of the BBB." (PMID 38999983, 2024). "The most commonly overexpressed genes in CNS tumors included TOP2A (67%), BIRC5 (59%), CDK4 (50%), BRIP1 (49%), NOTCH1 (41%), SMO (39%), and TP73 (39%)." (PMID 38347552, 2024). "A combined ribociclib (cyclin D1/CDK4 and CDK6 inhibitor) and everolimus treatment is utilized in the NCT03387020 phase I trial in children with recurrent/refractory primary CNS tumors, including MBs, with an intact RB1 protein." (PMID 31970590, 2020). "The maximum tolerated dose of palbociclib (CDK4/6 inhibitor) combined with chemotherapy (irinotecan and temozolomide) is evaluated in the NCT0370968 phase I trial in children with solid and CNS tumors." (PMID 31970590, 2020).
gastrointestinal tumors (3 papers, 2021 to 2025). "Our analysis of PPI networks identified 11 hub genes (Myd88, Traf6, Irf7, Cdk4, Ccnd2, Mapkap1, Prr5, Mpp3, Serpinb6b and Pvrl3) that were implicated in digestive tumours." (PMID 38434966, 2024). "The PPI networks identified 10 hub genes that were implicated in digestive tumour immunotherapy target TIM-3 (Myd88, Traf6, Irf7, Cdk4, Ccnd2, Mapkap1, Prr5, Mpp3, Serpinb6b and Pvrl3)." (PMID 38434966, 2024).
hematopoietic cancer (3 papers, 2021 to 2024). "The most potent chimera inhibited the proliferation of several hematopoietic cancer cells (DC50 values for CDK6 and CDK4 were 2.1 nM and more than 150–180 nM, respectively)." (PMID 39598723, 2024).
metabolic disease (3 papers, 2018 to 2025). A congenital disorder (due to inherited enzyme abnormality) or acquired (due to failure of a metabolically important organ) disorder resulting from an abnormal metabolic process. "In addition to elucidating a new role of CDK4 in the control of energy homeostasis, the effects of CDK4 depletion in BAT function justify to set up new studies based on the use CDK4 inhibitors for the treatment of metabolic diseases." (PMID 32657019, 2020).
Bacterial Infection (2 papers, 2015 to 2020). "Patients treated with CDK4/6 inhibitors are susceptible to viral or bacterial infections, the rate of infections in PALOMA-3 was 42% and were not reported in PALOMA-2." (PMID 32582373, 2020).
breast NECs (2 papers, 2020 to 2024). "The present report provides a new treatment strategy by incorporating CDK4/6 inhibitors in the therapeutic armamentarium of breast NECs." (PMID 39021492, 2024). "Although our current knowledge regarding therapeutic management of breast NECs is scarce and based mainly on case reports, CDK4/6 inhibitors are being proposed as another potential targeted therapy." (PMID 39021492, 2024). "Herein, we present the first case ever reported, concerning a female patient with de novo metastatic breast NEC who received hormonal therapy, a combination of a CDK4/6 inhibitor palbociclib with letrozole and triptorelin, as first‐line treatment with significant clinical and radiological response." (PMID 39021492, 2024).
peripheral neuropathy (2 papers, 2021 to 2025). A disorder affecting the peripheral nervous system. "Therefore, it is conceivable that off-target inhibition of neuronal CDK5 (or other related kinases) by CDK4/6 inhibitors could disrupt normal neuronal function and contribute to the development of peripheral neuropathy in a subset of patients." (PMID 41458615, 2025).
gastrointestinal disorders (1 paper, 2023). "In general, gastrointestinal disorders are the most frequent events for abemaciclib, and for this reason, this CDK4/6 inhibitor should not be recommended in patients with gastrointestinal comorbidities." (PMID 37895811, 2023).
kidney diseases (1 paper, 2023). "Additionally, the review explores the various therapeutic strategies and challenges associated with using CDK4/6 inhibitors for treating kidney diseases." (PMID 37686364, 2023). "Future research should prioritize investigating the role and mechanism of CDK4/6 inhibitors in treating kidney diseases by utilizing animal models and conducting in vitro cell experiments." (PMID 37686364, 2023). "Current studies have identified the renoprotective effect of CDK4/6 inhibitors, presenting a novel idea and potential direction for treating kidney diseases in the future." (PMID 37686364, 2023). "A deeper understanding of the mechanism and role of CDK4/6 inhibitors in kidney disease will aid in the development of more effective drugs for the treatment of these conditions." (PMID 37686364, 2023). "However, the utilization of CDK4/6 inhibitors for the treatment of renal diseases is currently underexplored, with existing research primarily limited to animal or in vitro cellular models." (PMID 37686364, 2023). "Remarkably, CDK4/6 inhibitors have demonstrated impressive efficacy in treating non-cancerous conditions, including certain kidney diseases." (PMID 37686364, 2023).
neuromuscular disease (1 paper, 2011). "In this report, we describe the isolation of immortalized human myoblast lines from a wide range of neuromuscular diseases, using a combination of hTERT and CDK-4." (PMID 22040608, 2011).
psychiatric disorder (1 paper, 2024). A disorder characterized by behavioral and/or psychological abnormalities, often accompanied by physical symptoms. "Thirdly, it was indeed challenging to discern whether psychiatric disorders in each case were induced by breast cancer, other drugs, or by CDK4/6i." (PMID 39009505, 2024). "Therefore, we speculate that CDK4/6i inhibit the CDK4/6‐Cyclin complex D in neural precursor cells, potentially leading to impaired neurogenesis and consequently inducing psychiatric disorders." (PMID 39009505, 2024). "The specific mechanism by which CDK4/6i induce psychiatric disorders is not yet clear." (PMID 39009505, 2024).